FGFR2 (fibroblast growth factor receptor 2)
Diseases named in the same sentence as FGFR2 in open-access papers (continued):
Sharing a sentence is not in itself a finding about the gene and the disease.
craniosynostosis (continued). "Apert syndrome (AS), also known as type I acrocephalosyndactyly, is a rare congenital condition characterized by craniosynostosis resulting from missense mutations in the fibroblast growth factor receptor 2 (FGFR2) gene." (PMID 38021759, 2023). "Except for Carpenter syndrome, which is linked to mutations in RAB23 (Ras-associated protein), all craniosynostosis syndromes result from FGFR2 gene mutations." (PMID 38021759, 2023). "In humans, FGFR mutations have been associated with craniosynostosis in patients with Apert and Crouzon syndromes (FGFR2 gain-of-function mutation) and Muenke syndrome (FGFR3 gain-of-function mutation)." (PMID 37325554, 2023). "Apert syndrome (AS), also known as type I acrocephalosyndactyly, is a rare congenital condition of craniosynostosis caused by missense mutations in the fibroblast growth factor receptor 2 (FGFR2) gene." (PMID 38021759, 2023). "This review meticulously evaluated AS, a rare congenital condition of craniosynostosis caused by mutations in the FGFR2 gene." (PMID 38021759, 2023). "Activating mutations in fibroblast growth factor receptor 2 (FGFR2) cause several craniosynostosis syndromes by affecting the proliferation and differentiation of osteoblasts, which form the calvarial bones." (PMID 35574015, 2022). "Monoallelic FGFR2 variants are associated with three syndromic forms of craniosynostosis, namely Apert (OMIM #101200), Crouzon (OMIM #123500) and Pfeiffer (OMIM #101600) syndromes." (PMID 35885943, 2022). "According to their monogenic inheritance, some authors propose to group these syndromes in a single spectrum of conditions termed “FGFR2-associated craniosynostosis syndromes”, including also clinically intermediate forms." (PMID 35885943, 2022). "A similar effect on splicing was demonstrated for other synonymous FGFR2 variants, such as p.(Pro361=), that is associated with mild Crouzon phenotype and reduced penetrance of craniosynostosis." (PMID 35885943, 2022). "Mutations in the FGFR2 gene with incomplete penetrance have been reported to cause a syndromic form of craniosynostosis with ID/DD." (PMID 35813072, 2022). "In the present study, all of the syndromic craniosynostosis subjects were genetically proven to have pathological or likely pathological mutations of FGFR2/3." (PMID 33731768, 2021). "Craniosynostosis syndromes are frequently associated with mutations in fibroblast growth factor receptors (FGFR2 or FGFR3) which play an important role in bone growth, particularly during embryonic development and are complexed with ECM components." (PMID 33974636, 2021). "Crouzon syndrome is an autosomal dominant genetic disorder caused by mutations in fibroblast growth factor receptor 2 (FGFR2) and one of the most common types of craniosynostosis." (PMID 33725872, 2021). "Gain-of-function mutation in Fgfr2 leads to Ffgr2-related craniosynostosis and mandibular dysmorphogenesis, demonstrating that Fgfr2 influences cartilage and intramembranous bone formation." (PMID 34299147, 2021). "The coronal cranial suture is prematurely fused in many individuals with syndromic craniosynostosis, and particularly in those with mutations in FGFR2 or Twist." (PMID 32916911, 2020). "In humans, omphalocele is reported in two case studies of Aperts syndrome, which is caused by Fgfr2 mutations, but is otherwise known as a craniosynostosis pathology." (PMID 32907848, 2020). "In summary, we quantitatively analyzed prenatal mandibular morphology in mouse models carrying mutation variants of Fgfr2 that are associated with craniosynostosis syndromes when present in humans." (PMID 31064775, 2019). "Our results demonstrate an intrinsic difference in mandibular morphology of newborn mice carrying FGFR2-related craniosynostosis mutations." (PMID 31064775, 2019). "Crouzon syndrome (CS), which results from fibroblast growth factor receptor 2 mutations, is associated with craniosynostosis, exophthalmos, and other symptoms." (PMID 31640617, 2019).
craniosynostosis (continued). "Crouzon syndrome (CS), caused by fibroblast growth factor receptor 2 (FGFR2) mutations, is associated with craniosynostosis." (PMID 31640617, 2019). "A genetic cause accounts for ∼25% of craniosynostosis cases, most frequently due to coding mutations in FGFR2, FGFR3, and TWIST1 (Wilkie, Johnson, & Wall, 2017)." (PMID 30040876, 2018). "Mutation of the exon IIIa of FGFR2 can cause AS because this mutation leads to increased bone differentiation rate of MSCs (Mesenchymal Stem Cells) and the development of craniosynostosis." (PMID 29868125, 2018). "FGFR2 encodes a fibroblast growth factor receptor whose mutations are responsible for the Crouzon syndrome, involving craniosynostosis and facial dysostosis with shallow orbits." (PMID 29848297, 2018). "Mutations in the FGFR2 gene are causative of multiple forms of syndromic craniosynostosis, including Crouzon syndrome." (PMID 30266836, 2018). "Syndromic craniosynostosis caused by mutations in FGFR2 is characterised by developmental pathology in both endochondral and membranous skeletogenesis." (PMID 28069589, 2017). "Human patients showing FGFR2 associated syndromes are characterized by craniosynostosis causing secondary alterations of the facial bones and facial structure." (PMID 28768473, 2017). "The most commonly mutated genes in syndromic craniosynostosis include FGFR2, FGFR3, and FGFR1, comprising the FGFR family." (PMID 29093661, 2017). "Syndromic craniosynostosis can be caused by mutations in the FGFR2 gene and is inherited in an autosomal dominant manner." (PMID 28069589, 2017). "For example the Crouzon syndrome (OMIM 123500) in humans is characterized by craniosynostosis but normal limbs and was initially shown to result from allelic mutations of the third immunoglobulin-like domain of FGFR2." (PMID 28768473, 2017). "As a result, these genetic mutations are likely to account for as many cases of craniosynostosis as the single mutation in a gene called FGFR2 that is currently known as the most frequent cause of craniosynostosis." (PMID 27687826, 2016). "Apert syndrome (AS) is a craniosynostosis condition caused by mutations in the Fibroblast Growth Factor Receptor 2 (FGFR2) gene." (PMID 26600631, 2015). "We provide experimental evidence that these mutations affect normal FGFR2 splicing and document the clinical consequences, which include a mild Crouzon syndrome phenotype and reduced penetrance of craniosynostosis." (PMID 25174698, 2014). "Mutations of fibroblast growth factor receptor 2 (FGFR2) account for a higher proportion of genetic cases of craniosynostosis than any other gene, and are associated with a wide spectrum of severity of clinical problems." (PMID 25174698, 2014). "The FGFR2 mutation in cranial suture chondrocytes, which increased cartilage proliferation and differentiation, ultimately caused craniosynostosis." (PMID 24489893, 2014). "Neuroanatomical abnormalities are a striking phenotype that is part of the wide range of abnormalities that characterize AS and are much more severe than the ones observed in other FGFR2 -associated craniosynostosis." (PMID 23593218, 2013). "Crouzon's syndrome (CS) is a rare autosomal dominant condition with multiple mutations of the fibroblast growth factor receptor (FGFR2) gene, which accounts for 4.8% of all cases of craniosynostosis." (PMID 25206185, 2013). "Homozygosity for the Fgfr2 gain-of-function Crouzon mutation in mice results in cleft palate, as well as, craniosynostosis indicating that elevated Fgf signaling also causes cleft palate." (PMID 24068957, 2013).
craniosynostosis (continued). "Ligand-dependent and ligand-independent gain-of-function mutations in FGFR2 lead to a common bilateral coronal craniosynostosis but to very distinct abnormalities in AS and CS." (PMID 23593218, 2013). "We did not observe specific phenotypic differences between IL11RA and FGFR2 caused craniosynostosis." (PMID 24498618, 2013). "For example, mutations that causes abrogation of the Fgf receptor 2 (Fgfr2) cause hypertelorism, craniosynostosis, and mid-facial hypoplasia." (PMID 23055979, 2012). "All have been previously linked with calvarial development and, in the case of FGFR2, with craniosynostosis." (PMID 18076769, 2007). "For example, syndromes associated with genetic variants in fibroblast growth factor receptor 2 (FGFR2), including Apert, Pfeiffer, Crouzon, and bent bone dysplasia, often present with multi-suture craniosynostosis, as well as a persistently open anterior fontanelle (AF)." (PMID 39775862, 2025). "Similarly, mouse models carrying specific FGFR2 splice variants exhibit delayed mineralization of the calvarium, craniosynostosis, and shortened long bones, further supporting the role of FGFR2 in bone formation." (PMID 40362441, 2025). "The generation of patient-derived hiPSCs provides a unique opportunity to gain a better understanding of variant-specific FGFR2-linked craniosynostosis at a molecular level in the patient-specific genomics context and illustrates the necessity for the development of personalized therapies." (PMID 40843495, 2025). "Several craniosynostosis syndromes, including Crouzon, Apert, Pfeiffer, Antley-Bixler, Beare-Stevenson cutis gyrata, Jackson-Weiss, Bent bone dysplasia, and Seathre-Chotzen syndromes, arise from pathogenic variants in FGFR2 (MIM 176943)." (PMID 40261605, 2025). "In patients with the Antley-Bixler syndrome, characterized by craniosynostosis, brachycephaly, midface hypoplasia, and choanal atresia and/or stenosis, variants have been found not only in FGFR2, but also in the gene encoding cytochrome p450 oxidoreductase (POR)." (PMID 37441579, 2023). "Given the recent breakthrough of NGS techniques, such as WES, we reckon that the analysis of FGFR2 should be included, and its variants should be taken in mind in patients with neurodevelopmental disorder, especially in association with craniosynostosis and body overgrowth." (PMID 37733178, 2023). "However, the variants of FGFR1 and FGFR2 have been found in hypogonadotropic hypogonadism 2 with anosmia (rs121909642), Pfeiffer syndrome, craniosynostosis syndrome (rs121918506), and in LADD syndrome (rs121918509), respectively." (PMID 34714320, 2021). "Similarly, the Fgfr2cC342Y mutation is one of the more strongly activating mutations of Fgfr2 causing craniosynostosis, being ligand-independent and generating a higher basal level of phospho-ERK compared to, for example, Apert syndrome mutations." (PMID 30048539, 2018). "Low Fgf8b expression mimics the craniosynostosis seen with particular FGFR2-activating mutations." (PMID 29752281, 2018). "We speculate that aspects of the malformation seen in homozygous mice may contribute to the high incidence of hearing loss reported in FGFR2-related cases of syndromic craniosynostosis, including 74% of CPS patients and warrants a more detailed investigation." (PMID 28069589, 2017).
craniosynostosis (continued). "Subsequently most mutations identified in the human FGFR2 gene localize to just two exons, encoding the third immunoglobulin-like domain in the extracellular region, resulting in syndromic craniosynostosis including Apert, Crouzon and Pfeiffer syndromes (OMIM 101600)." (PMID 28768473, 2017). "Indeed, mutations in FGFR1 and FGFR2 account for the craniosynostosis and chondrodysplasia syndromes in humans, suggesting that both FGFRs are important for endochondral and intramembranous bone formation." (PMID 25873956, 2015). "Key words:Craniosynostosis, Pfeiffer syndrome, mutation, FGFR2." (PMID 25129254, 2015). "Interestingly, several mutations in exxons 8 and 10 of the FGFR2 locus are also associated with other craniosynostosis syndromes, such as Crouzon and Jackson-Weiss." (PMID 25129254, 2015). "We used SNP analysis to determine whether FGFR1, FGFR2, or Twist1 were associated with the craniosynostosis phenotype of the rabbit colony." (PMID 23738319, 2013). "We used genomic DNA obtained from inbred, randomly selected CS rabbits to determine whether the SNPs we identified in FGFR1, FGFR2, and Twist1 were linked to the presence of craniosynostosis." (PMID 23738319, 2013). "Apert syndrome (OMIM 101200) is characterized by premature closing of the sutures between the bones of the skull (craniosynostosis) due to gain of function mutations in the receptor tyrosine kinase fibroblast growth factor receptor 2 gene (FGFR2), one of four such receptors (FGFR1-4)." (PMID 22359510, 2012). "Many other pathogenic missense mutations of FGFR2 have been described in patients with craniosynostosis (typically with diagnoses of Crouzon, Pfeiffer or Beare-Stevenson syndromes) but these are associated with less severe abnormalities of the limbs than are present in Apert syndrome." (PMID 21943124, 2011). "Apert syndrome, which was well described by a number of authors earlier is a rare congenital anomaly, appearing with a frequency of 1 in 55,000 to 90,909 live births is one of the five craniosynostosis syndromes caused by allelic mutations of the fibroblast growth-factor receptor 2 (FGFR2)." (PMID 17286873, 2007). "Interestingly, mutations in the same FGFR (either FGFR1, FGFR2 or FGFR3) can result in different craniosynostosis syndromes, thus implicating a common pathologic mechanism with FGFR gain of function in Pfeiffer, Apert, Muenke, and Beare-Stevenson syndromes." (PMID 16740155, 2006). "The perturbation of both BMP signaling pathways, affected by GDF6 mutations, and FGF signaling pathways, affected by FGFR2 mutations, may collectively contribute to the complex phenotype observed in patients with cervical segmental insufficiency and craniosynostosis." (PMID 38561822, 2024). "However, FGFR2 mutations contribute to the majority of craniosynostosis syndromes in humans." (PMID 37325554, 2023). "According to our results, the disruption of the osteogenic differentiation by the Erk1/2 signaling pathway could be one of the reasons for the overgrowth of bone tissues in the primary patient sutures and resulting in craniosynostosis in the genetic background of FGFR2 mutation p.Cys342Arg." (PMID 36231091, 2022). "Less frequently, FGFR2 pathogenic variants may cause other craniosynostosis forms." (PMID 35885943, 2022).
craniosynostosis (continued). "It is unknown how Phex mutations lead to craniosynostosis, but, similar to studies of human patients with Fgfr2-associated craniosynostosis, these patients also commonly have paradoxical heterotopic calcification of normally nonmineralizing tissues, such as tendons and ligaments." (PMID 23762837, 2013). "Craniosynostosis (CS), characterized by the premature fusion of cranial sutures, often results from aberrant activation of Fibroblast growth factor receptor 2 (FGFR2), a major regulator of osteogenic differentiation in cranial mesenchyme." (PMID 41647289, 2025). "The most prevalent forms of syndromic craniosynostosis include Muenke type (FGFR3 mutations), Saethre-Chotzen type (TWIST1 mutations), Crouzon type (FGFR2 mutations), Pfeiffer type (FGFR1 and FGFR2 mutations), and Apert type (FGFR2 mutations)." (PMID 40723825, 2025). "Most patients with FGFR2-related conditions experience craniosynostosis involving both minor and major suture fusion." (PMID 40261605, 2025). "The hiPSC lines described here can support fundamental research on variant- and patient-specific disease mechanisms, aberrant downstream signaling and alterations in osteogenic differentiation in FGFR2-related craniosynostosis." (PMID 40843495, 2025). "Midfacial hypoplasia can be severe, but is variable within and across FGFR2-related craniosynostosis syndromes." (PMID 38347173, 2024). "Comprising more than 20 exons, FGFR2 has been scrutinized for mutations, with Exons 9 and 10 encoding the extracellular immunoglobulin-like III (IgIII) domain—a hotspot for mutations in craniosynostosis syndromes." (PMID 38561822, 2024). "Mutations in the genes encoding FGFR1, FGFR2, and FGFR3 can cause skeletal dysplasias and craniosynostosis syndromes." (PMID 39061616, 2024). "N-glycosylation of FGFR2 was shown to regulate cellular trafficking and autoactivation of the receptor, and mutations in FGFR2 and FGFR3 that disrupt N-glycosylation were linked with craniosynostosis syndromes." (PMID 37012400, 2023). "The genes most closely associated with syndromic craniosynostosis are the FGFR genes (mainly FGFR1, FGFR2, FGFR3), the TWIST gene, and genes of the ephrin family (EFNB1)." (PMID 38222144, 2023). "Clinically, the phenotype shows overlap with FGFR2-driven craniosynostosis, usually Crouzon syndrome." (PMID 37175668, 2023). "U0126, a specific MEK1/2 inhibitor but low potency drug, was used with encouraging results in the treatment of an FGFR2-induced craniosynostosis mouse model, and we have shown that it can effectively regulate Erf localization and function." (PMID 37175668, 2023). "Activated site mutations and extracellular domain in-frame deletions of FGFR2 were also identified in ICC and craniosynostosis syndromes as well." (PMID 37964396, 2023). "Gain-of-function mutations in fibroblast growth factor receptor 1 (FGFR1), FGFR2 and FGFR3 are responsible for many craniosynostosis syndromes, including bent bone dysplasia and Crouzon, Apert, Pfieffer, Beare–Stevenson and Muenke syndromes, among others." (PMID 35451466, 2022). "Saethre Chotzen syndrome is characterized by mild craniosynostosis of different cranial sutures and syndactyly and is caused by the autosomal dominant mutation of TWIST gene and the FGFR2 gene." (PMID 34633507, 2022). "We used an Fgfr2-C342Y transgenic mouse line that is kept on a CD-1 background, that in our hands displays patent sutures at birth, followed by the onset of craniosynostosis which is usually complete by P21." (PMID 35690633, 2022).